AR (androgen receptor)
Diseases named in the same sentence as AR in open-access papers (continued):
Sharing a sentence is not in itself a finding about the gene and the disease.
prostate carcinoma (continued). "Nuclear AR expression based on immunohistochemistry (IHC) is the most widely used marker of active AR signaling, and correlates with the response to ADT in prostate cancer." (PMID 28208703, 2017). "CD9 is an upstream regulator of AR, and exosomes can deliver CD9 to modulate paracrine signaling to mediate the growth of androgen deprived prostate cancer." (PMID 29228644, 2017). "Multiple mechanisms of docetaxel resistance exist in prostate cancer, including ABC transporters, glucocorticoid receptor (GR), androgen receptor (AR) splicing, epithelial plasticity, and stem cells." (PMID 28455956, 2017). "In prostate cancer, MC increased stem/progenitor cell population via altering LncRNA-HOTAIR/PRC2-androgen receptor- (AR-) MMP9 signals." (PMID 28337221, 2017). "Since AR plays a crucial role in prostate cancer cell proliferation, and is a common therapeutic target, we assessed possible roles for CREB3L4 in the AR signal cascade." (PMID 28338058, 2017). "In a castration-resistant prostate cancer model, EZH2 methylated AR and modulated AR recruitment to its target sites." (PMID 28410242, 2017). "It has been reported that quercetin can inhibit the expression and activity of androgen receptor (AR) through Sp1-mediated blockage of c-Jun N-terminal kinase (JNK) signaling pathway, therefore reducing the invasiveness of prostate cancer cells." (PMID 28264020, 2017). "Like the AR, NRIP is an androgen-regulated gene and our current data support the view that it acts as an oncoprotein in prostate cancer." (PMID 28212551, 2017). "For prostate cancer cells, GATA2 and OCT1 work in a hierarchical network as GATA2 is recruited with AR, followed by OCT1 binding to its motifs." (PMID 28264478, 2017). "There are also reports that Cdk5 mediates prostate cancer progression through STAT3 and AR signaling." (PMID 28288624, 2017). "Prostein and PSA correctly detected 82% of cases, HOXB13 and PSA labeled 94.2% of cases correctly, AR and PSA detected 100% of cases, and ERG and PSA recognized 88% of prostate cancer metastases." (PMID 28555048, 2017). "In the prostate cancer cell line LNCaP, NRIP displaced DDB2 to prevent DDB2 degrading the AR in the CUL4-DDB2-E3 ligase complex." (PMID 28212551, 2017). "Increased IL-8 of prostate cancer cells signals through CXCR1 and CXCR2 to induce transcription of androgen receptor (AR) and to activate ERK and Akt, in turn, promoting cancer growth and survival." (PMID 29379802, 2017). "The result indicated that AR was highly expressed in neuroblastoma cell lines, Neuro2A, and SH-SY5Y, as well as prostate cancer cell line LNCaP, glioma cell lines, U87MG and U251MG." (PMID 28423563, 2017). "When AR signaling is lost during ADT, increased CXCR7 expression drives EGF-induced mitogenic signaling as one mechanism that potentially facilitates prostate cancer cell survival." (PMID 28596572, 2017). "In prostatic cancer cells with downregulated AR expression by short interfering RNA, treatment with sorafenib increased apoptosis in an additive manner, suggesting that there might be a potential to use inhibitors of AR in HCC as an adjuvant therapy option for sorafenib-resistant HCC patients." (PMID 28475115, 2017). "Collectively, this study delineated a linear co-relation between AR, c-Myc and FKBP52 in prostate cancer." (PMID 28852180, 2017). "(C) ChIP-seq tracks for AR at the GR (NR3C1) locus in patient-matched normal prostate tissue and primary prostate cancer tissue samples." (PMID 28891793, 2017). "Our results support the idea that AR-expressing luminal stem-like cells could function as cancer-initiating and relapse-initiating cells in castration-resistant prostate tumors, suggesting that novel strategies targeting this cell population should be considered in the treatment of prostate cancer." (PMID 28446230, 2017). "Anti-AR drugs, such as cisplatin, niclosamide, ASC-J9, EPI-001, and even miRNA or lncRNA, also suppress prostate cancer." (PMID 29149895, 2017).
prostate carcinoma (continued). "The AR agonist DHT at nanomolar concentrations produced a significant decrease in PPARγ mRNA and protein levels within two AR-positive human prostate cancer cell lines: the castration-sensitive VCaP cells and castration-resistant C4-2 cell line." (PMID 29181019, 2017). "In terms of TMPRSS2:ERG, we previously developed a PI polyamide targeting a common sequence in AR-related DNA break points among TMPRSS2 and ERG gene loci to repress TMPRSS2:ERG expression and prostate cancer cell growth." (PMID 28264478, 2017). "Progression of prostate cancer (PC) to castration-recurrent growth (CRPC) remains dependent on sustained expression and transcriptional activity of the androgen receptor (AR)." (PMID 28055971, 2017). "Given the critical role of FKBP52 in AR signaling in cellular and whole animal models, both in vitro and in vivo, FKBP52 has emerged as a potential target for the treatment of prostate cancer." (PMID 28252832, 2017). "For instance, in prostate cancer cells, IGF-I is thought to indirectly stimulate the androgen receptor via crosstalk with IGF-IR to induce the transformation of prostatic epithelial cells." (PMID 27661006, 2017). "A comparative gene expression analysis conducted between human prostate cancer and BPH tissues revealed that several genes from the AR signaling pathway were up regulated." (PMID 28852180, 2017). "Data from the in vitro study further suggested that the efficacy of DR17 treatment resulted, in part, from the targeting of multiple prostate cancer relevant signaling pathways including PI3K/AKT/mTOR and HSP90/HSP70/AR." (PMID 28350865, 2017). "Because of the fundamental role of androgens in prostate development as well as prostate cancer, our objective was to investigate if the effect of CH223191/ PP2 also affected gene expression of AR and downstream target gene KLK3 (PSA)." (PMID 28671964, 2017). "Our data revealed that gp78, Hrd1, SVIP and AR showed increased expression (p < 0.05 for AR and p < 0.005 for gp78, Hrd1, SVIP) in prostate cancer tissues." (PMID 28091582, 2017). "In prostate cancer cells, TGF-β induces AR activation of its target genes, while AR also represses TGF-β signaling through interaction with Smad3." (PMID 29249975, 2017). "Recently the first AR NTD antagonist, a prodrug of EPI-002, started Phase 1 clinical trials for prostate cancer patients that have failed abiraterone and/or enzalutamide (Clinical trials NCT02606123)." (PMID 28306720, 2017). "The expression of the androgen receptor gene in prostate cancer cells is regulated by androgens, and both androgen receptor (AR) and growth factor pathways can trigger ERK MAPK signaling in prostate cancer cells." (PMID 28830537, 2017). "Since AR activity and lipid metabolism appear important in prostate cancer, here we investigate ECI2, an AR-target gene." (PMID 28415728, 2017). "Taken together, these data suggest that a novel AR target gene, ECI2, supports aberrant metabolic homeostasis of prostate cancer cells." (PMID 28415728, 2017). "Finally, we tested whether AR− CARNs can serve as the cell of origin for prostate cancer." (PMID 28112153, 2017). "Collectively, these results indicated that knockdown of ID4 enhances tumorigenicity of prostate cancer cells in the CRPC conditions, more importantly through FKBP52‐mediated AR signaling." (PMID 28252832, 2017). "Since a reciprocal feedback between the AR and the PI3K pathways has been demonstrated in prostate cancer, a combination of inhibitors targeting the PI3K pathway and anti-androgens, such as abiraterone and enzalutamide is currently in clinical trials." (PMID 28915623, 2017). "Here we show that overexpression of the AR NTD to generate decoy molecules inhibited both the growth and progression of prostate cancer in castrated hosts." (PMID 28306720, 2017). "Collectively, we demonstrated that CREB3L4 is required for proliferation of prostate cancer cells, and that CREB3L4 is a crucial activator of AR function." (PMID 28338058, 2017).
prostate carcinoma (continued). "Studies have confirmed that expressions of AR and c-Myc are strongly correlated in metastatic CRPC and c-Myc promotes the ligand-independent survival of the prostate cancer cell through its effect on AR14." (PMID 28852180, 2017). "Therefore, AR-PGC-1α crosstalk may compromise PPARγ function within prostate cancers." (PMID 29181019, 2017). "The relationship between GGH expression, androgen receptor (AR) expression, and ERG activation was analyzed because of the central role of AR for prostate cancer, and because ERG activation is the most frequent molecular alteration in this tumors." (PMID 28146062, 2017). "AR-V7 presence detected by immunofluorescent staining was predictive of poor response to AR signaling inhibitors and improved response to taxane therapy, suggesting a potential role for CTC evaluation in directing advanced prostate cancer therapy." (PMID 28191452, 2017). "On the other hand, interestingly, we found that in prostate cancer cells DANCR knockdown decreased the promotion of invasion and migration by the treatment of enzalutamide, which is an AR inhibitor." (PMID 27191265, 2016). "Furthermore, AR knockdown in urotehlial cells by intravesical instillation of antisense oligonucleotides, as shown with those of heat shock protein 27 in BC, is a potential treatment option to avoid systemic adverse effects associated with ADT currently used for the treatment of prostate cancer." (PMID 26885620, 2016). "In clinical prostate cancer specimens, KLF4 levels were positively correlated with miR-1 and AR levels." (PMID 27991915, 2016). "Based on these data, we decided to analyse the possible metabolic adaptations that enable prostate cancer cell survival despite the significant down-regulation of prominent prostate cancer oncogenes, c-MYC and AR." (PMID 26824323, 2016). "Androgen receptor (AR) and PI3K/AKT/mTORC1 are major survival signals that drive prostate cancer to a lethal disease." (PMID 27557496, 2016). "Our research also confirms that when using nocodazole or 2-ME to arrest prostate cancer cell at G2/M phase, PC-1 overexpression reduces AR expression levels, while duel PC-1/CHIP knockdown protects AR from nocodazole or 2-ME induced degradation." (PMID 27835608, 2016). "c-FLIP is aberrantly expressed in both high grade prostate cancer and CRPC and is a direct target for AR-mediated transcriptional activity; the c-FLIP gene promoter contains defined androgen response elements (AREs)." (PMID 27729622, 2016). "We have previously shown that combining the AR antagonist bicalutamide with the HDAC inhibitor vorinostat synergistically induces growth arrest and cell death in prostate cancer cells." (PMID 26907477, 2016). "In prostate cancer cells, upon ligand binding, USP22 is recruited (and also promotes AR recruitment) to the promoter regions of AR- dependent genes such as KLK2, KLK3/PSA, TMPRSS2 and FKBP5." (PMID 27057639, 2016). "In cultured prostate cancer cell lines, GATA2 has been shown to function as a pioneer factor for AR genomic binding and function, while surprisingly GATA3 is not expressed." (PMID 27374105, 2016). "Two AR antagonists, bicalutamide and enzalutamide, and a CYP17A1 inhibitor, abiraterone, are currently used in the clinical treatment of prostate cancer." (PMID 27918430, 2016). "Interest in SINT1 is drawn from the fact that it blocks transactivation of the AR NTD and inhibits AR-dependent proliferation of prostate cancer cells in vitro." (PMID 27576691, 2016). "Co-immunoprecipitation assays demonstrated a physical interaction between the AR and ERG proteins in vCaP cells as well as prostate cancer tissues." (PMID 27208692, 2016). "These cell lines are known to express androgen receptor (AR) and prostate specific antigen (PSA), two well-known prostate cancer markers." (PMID 27835867, 2016).
prostate carcinoma (continued). "To examine the roles of intracellular SGTA and REIC/DKK-3 and their interaction in AR signal transduction, we expressed and co-expressed these proteins in PC3 prostate cancer cells under additional AR co-expression." (PMID 26658102, 2016). "Our results indicate that androgen-AR signaling up-regulates TIMP2/3 and DANCR impedes this up-regulation in prostate cancer cells." (PMID 27191265, 2016). "In prostate cancer cell lines, FOXA1 is required for androgen receptor activation, and over-expression of FOXA1 increases AR binding throughout the genome." (PMID 26986977, 2016). "Both AR protein and mRNA were found to be reduced by TQ treatment in both LAPC4 and LNCaP human prostate cancer cells." (PMID 26986969, 2016). "On the other hand, DANCR knockdown facilitated the upregulation of TIMP2/3 and the suppression of invasion and migration by androgen-AR, while DANCR knockdown decreased the promotion of invasion and migration in prostate cancer cells by enzalutamide treatment." (PMID 27191265, 2016). "In cultured prostate cancer cells, GATA2 is essential for the expression of a subset of AR target genes such as PSA and NKX3.1." (PMID 27374105, 2016). "Current treatments for prostate cancer include surgical and medically induced castration and androgen deprivation therapy (ADT) using androgen receptor (AR) antagonists." (PMID 28058266, 2016). "This level is similar to previous reports of other LBD-lacking AR variants (expressed at <5% of the levels of wild-type AR in breast and prostate cancer cell lines and tissues), although they may be expressed more highly in some prostate cancer cell lines and clinical prostate cancer specimens." (PMID 28035996, 2016). "Combining ACLYi with either of two AR antagonists (ENZ or bicalutamide) potently suppressed growth in both CRPC and hormone naïve AR+ prostate cancer cell lines." (PMID 27248322, 2016). "In cultured prostate cancer cells, GATA2 coordinates with androgen receptor (AR) to regulate gene transcription." (PMID 27374105, 2016). "In cultured prostate cancer cells, GATA2 regulates AR gene expression and also acts as a pioneer factor to cooperate with AR to regulate AR target gene expression." (PMID 27374105, 2016). "To address this, in this study we conduct a deep sequencing analysis of AR in tissues derived from metastatic CRPC, localized CRPC and therapy-naive prostate cancer." (PMID 27897170, 2016). "APOD is a direct transcriptional target of the AR, and a DHT-dependent secretion of APOD has been observed in prostate cancer cells." (PMID 27583472, 2016). "In prostate cancer, TCF21 interacts with AR and inhibits its transactivation through the recruitment of HDAC1." (PMID 27028856, 2016). "Previous studies have shown that 2-ME, a naturally occurring estrogen metabolite, induces mitotic arrest in prostate cancer cells, thus activating CHIP and degrading AR." (PMID 27835608, 2016). "DATS incubation with prostate cancer cells (LNCaP, C4-2, and TRAMP-C1) decreases the protein expression of AR following the suppression of intracellular and secreted levels of PSA." (PMID 27019751, 2016). "Furthermore, with the clue that recent studies reported androgen/AR axis increased Nanog expression in prostate cancer cells, and our previous study has identified Nanog as an important stemness regulator in HCC cells, we wondered whether the axis could impact on HCC cells stemness." (PMID 27167111, 2016). "Surprisingly, microarray analysis revealed knockdown of SSX2 also resulted in a knockdown of the androgen receptor (AR) and prostate specific membrane antigen (PSMA), both of which are intrinsically tied to prostate cancer disease progression." (PMID 27276714, 2016). "Anti-apoptotic and AR target gene c-FLIP is aberrantly expressed in human prostate tumors including CRPC; inhibition of c-FLIP sensitizes prostate cancer cells to apoptosis." (PMID 26872377, 2016).
prostate carcinoma (continued). "Therefore, we asked whether the central domain of Tab2 was also able to interact with other receptors, specifically with AR that plays a role in the response/resistance of prostate cancer cells to anti-androgenic drugs, in analogy to anti-estrogens in breast cancer cells." (PMID 27992601, 2016). "Our data are also the first to suggest a link between the AR and expression of GCNT1 in prostate cancer." (PMID 27428423, 2016). "We previously showed that the suppression of AR signaling not only inhibited prostate cancer cell proliferation and PSA secretion but also promoted CCL2 secretion, enabling prostate cancer cells to metastasize." (PMID 26701731, 2016). "In the case of prostate cancer cells, PRMT5 inappropriately modifies the androgen receptor, a protein that regulates the growth of normal prostate cells." (PMID 27183006, 2016). "In concordance with the tumor-suppressive effect mediated by KLF4 activation, we demonstrated that AR-induced KLF4 expression negatively regulates the proliferation and metastatic abilities of prostate cancer cells." (PMID 27991915, 2016). "To determine the impact of VT-464 on AR signaling, we measured the effects of VT-464 on a AR reporter construct, FKBP51-ARE-luciferase, which is activated in the presence of the synthetic androgen 1nM R1881 in C4-2B prostate cancer cells." (PMID 27748439, 2016). "In prostate cancer, PITX2 is an upstream regulator of a key transcription factor, the androgen receptor (AR)." (PMID 27716615, 2016). "Overexpression of EAF2 induced apoptosis in cultured prostate cancer cells as well as in prostate cancer xenograft tumors, and EAF2 knockdown in LNCaP cells enhanced the expression of androgen receptor (AR)-target genes, cell proliferation, and migration." (PMID 27058417, 2016). "In prostate cancer cells, EZH2 interacts with androgen receptor (AR) independently of PRC2, and functions as a transcriptional co-activator inducing the expression of AR target genes." (PMID 27793053, 2016). "In the case of AR, the molecule EPI–001 and its derivatives bind to the AR-NTD and have been presented as potential drugs that promote the regression of prostate cancer, a disease that is essentially under the regulation of the androgen receptor (AR)." (PMID 27583469, 2016). "We next validated the relationship between AR, KLF4 and miR-1 expression in human prostate cancer tissues from the Taylor Prostate Cancer Dataset and The Cancer Genome Atlas." (PMID 27991915, 2016). "In summary, this is the first report that both AR and EZH2 regulate RUNX1 and that RUNX1 was shown to have differential functions in androgen-dependent and androgen-independent prostate cancer cells." (PMID 25537508, 2015). "Based upon the co-localization of AR and CXCR7 proteins it is highly likely AR, CXCR7, and β-arrestin 2 form a ternary complex since β-arrestin 2 has been shown to bind both AR and CXCR7 in prostate-cancer cells." (PMID 25884570, 2015). "The androgen receptor (AR) surface-directed antagonist MJC13 inhibits AR function and proliferation of prostate cancer (PC) cells." (PMID 26332122, 2015). "Structurally, AR was noted to co-exist with EGFR and Src in EGF treated AR8 overexpressing prostate cancer cells." (PMID 25705125, 2015). "We performed a literature search using PubMed with the search terms: “androgen resistant”, “androgen independent”, “AR independent”, “AR resistant”, “castration-resistant”, “PC3”, “DU145”, and “prostate cancer”, which delivered 5,115 abstracts." (PMID 26603105, 2015). "More experiments are needed to define the relationship between AhR, AR and the differential effects of TCDD on prostate cancer at different stages." (PMID 26154658, 2015). "This notion is further demonstrated by the in vivo studies showing that over-expression of TRPM8 in the AR+ and TRPM8-expressing LNPaC cells promoted tumorigenicity of xenograft prostate cancer." (PMID 26512697, 2015).